SPPL2A (signal peptide peptidase like 2A)
Description:
Intramembrane-cleaving aspartic protease (I-CLiP) that cleaves type II membrane signal peptides in the hydrophobic plane of the membrane. Functions in FASLG, ITM2B and TNF processing. Catalyzes the intramembrane cleavage of the anchored fragment of shed TNF (TNF), which promotes the release of the intracellular domain (ICD) for signaling to the nucleus. Also responsible for the intramembrane cleavage of Fas antigen ligand FASLG, which promotes the release of the intracellular FasL domain (FasL ICD). Essential for degradation of the invariant chain CD74 that plays a central role in the function of antigen-presenting cells in the immune system (By similarity). Plays a role in the regulation of innate and adaptive immunity. Catalyzes the intramembrane cleavage of the simian foamy virus envelope glycoprotein gp130 independently of prior ectodomain shedding by furin or furin-like proprotein convertase (PC)-mediated cleavage proteolysis.
Synonyms: IMP3; PSL2; IMD86
Tractability: Small molecule: a high-quality ligand is known. Antibody: its Gene Ontology location is reachable by antibodies, with high confidence; UniProt predicts a signal peptide or a membrane-spanning region. PROTAC: ubiquitination databases record sites on it; its protein half-life has been measured; a small molecule that binds it is known.
Target class: Enzyme; Hydrolase
Gene: Protein-coding gene on chromosome 15 (50,702,266 to 50,765,948, reverse strand). Ensembl gene ENSG00000138600.
Subcellular location: Late endosome membrane; Lysosome membrane; Membrane
Subcellular location (Human Protein Atlas): Vesicles
Pathways (Reactome):
Signal Transduction: Regulation of TNFR1 signaling
Gene Ontology:
Molecular function: aspartic endopeptidase activity, intramembrane cleaving; protein binding; protein homodimerization activity
Biological process: membrane protein ectodomain proteolysis; membrane protein intracellular domain proteolysis; membrane protein proteolysis; regulation of immune response; regulation of tumor necrosis factor-mediated signaling pathway
Cellular component: cytoplasmic side of endoplasmic reticulum membrane; extracellular exosome; Golgi-associated vesicle membrane; late endosome; late endosome membrane; lumenal side of endoplasmic reticulum membrane; lysosomal membrane; membrane; plasma membrane; bounding membrane of organelle; cytoplasmic vesicle membrane
Genetic constraint (gnomAD): Loss-of-function variants: 8 observed, 13.44 expected, observed/expected ratio (o/e) 0.6, 90% interval 0.35 to 1.07. The upper end of that interval is the gene's LOEUF score, 1.07, which puts it in group 4 of 6, group 1 being the genes least tolerant of losing a copy. Missense variants: 167 observed, 168.35 expected, observed/expected ratio (o/e) 0.99, 90% interval 0.87 to 1.13. Synonymous variants: 63 observed, 57.97 expected, observed/expected ratio (o/e) 1.09, 90% interval 0.89 to 1.34.
Homologues: Orthologues: chimpanzee SPPL2A (99% identical), pig SPPL2A (90% identical), rabbit SPPL2A (87% identical), dog SPPL2A (86% identical), guinea pig SPPL2A (83% identical), rat Sppl2a (81% identical), mouse Sppl2a (80% identical), tropical clawed frog sppl2a (60% identical). Paralogues in human: SPPL2B (46% identical), SPPL2C (40% identical), SPPL3 (19% identical), HM13 (18% identical).
Diseases named in the same sentence as SPPL2A in open-access papers:
SPPL2A is named in the same sentence as 21 diseases in open-access papers, as found by Europe PMC text mining. Sharing a sentence is not in itself a finding about the gene and the disease. The quoted sentences say what the papers report.
melanoma (3 papers, 2021 to 2025). A malignant, usually aggressive tumor composed of atypical, neoplastic melanocytes. "Proteomic profiling further identified the enrichment of SPPL2A in the melanoma exosomal cargo (a molecule previously correlated with diminished disease-free and overall survival) suggesting its potential utility as a prognostic indicator within the extracellular vesicle compartment." (PMID 40805206, 2025). "Interestingly, a recent study using transcriptomic profiling of canine cancers identified TRPM7 as a biomarker of melanoma and SPPL2A as a highly relevant target." (PMID 35053440, 2022). "In the case of melanoma (MEL), high novelty targets are SPPL2A, CHL1, AP4E1, SECISBP2L, and COPS2." (PMID 34570764, 2021). "In the present study, we showed that TRPM7, SPPL2A, and GABPB1 are involved in the proliferation of canine and human non-UV-induced melanomas." (PMID 35053440, 2022).
acral melanoma (1 paper, 2022). "In the Cancer Genome Atlas, we found one case of acral melanoma (TCGA-ER-A19T-01) harboring a strong focal amplification on chromosome 15 (orthologous to canine chromosome 30) encompassing the candidate oncogenes SPPL2A, USP8, TRPM7, and GABPB1." (PMID 35053440, 2022).
allergies (1 paper, 2020). "In this case decreased SPPL2a proteolytic activity would prolong immune responses possibly also leading to autoimmunity or allergies, while increased cleavage by SPPL2a could stop the immune response before the threat is under control, showing the importance of fine-tuning such processes." (PMID 33381526, 2020).
atherosclerosis (1 paper, 2020). A disease characterized by the build-up of fatty material and calcium deposition in the arterial wall resulting in partial or complete occlusion of the arterial lumen. "SPPL2a/b mediate the turnover of this fragment, terminate signaling and by this means control the development of atherosclerosis." (PMID 32052089, 2020). "Recently, an important impact of SPPL2a and SPPL2b on the development of atherosclerosis was uncovered." (PMID 32052089, 2020). "Atherosclerosis was significantly increased in SPPL2a/b−/− mice as compared to controls based on the development of larger and more advanced plaques." (PMID 32052089, 2020). "Altogether these results demonstrate that SPPL2a/b confine and limit the development of atherosclerosis, which leads to cardiovascular diseases and therefore represents a major cause of morbidity and mortality." (PMID 32052089, 2020). "Atherosclerosis was induced in wild type and SPPL2a/b−/− mice via overexpression of a gain-of-function mutant of the Proprotein Convertase Subtilisin/Kexin type 9 (PCSK9) in order to deplete the LDL receptor in combination with a high fat/high cholesterol diet." (PMID 32052089, 2020).
B-cell neoplasm (1 paper, 2015). A group of heterogeneous lymphoid tumors generally expressing one or more B-cell antigens or representing malignant transformations of B-lymphocytes. "Further, recent work from SPPL2a deficient mice suggests that SPPL2a may be a target for immunomodulatory therapies and possibly in B-cell neoplasms." (PMID 26046535, 2015).
breast carcinoma (1 paper, 2025). "Exon inclusion in SPPL2A and exon exclusion in SMARCA1 were observed not only in LADC, but also in MDA-MB-231 cells, a breast cancer cell line with a truncating CMTR2 mutation." (PMID 41198678, 2025).
hepatitis C (1 paper, 2015). "The signal peptide peptidases (SPPs) are biomedically important proteases implicated as therapeutic targets for hepatitis C (human SPP, (hSPP)), plasmodium (Plasmodium SPP (pSPP)), and B-cell immunomodulation and neoplasia (signal peptide peptidase like 2a, (SPPL2a))." (PMID 26046535, 2015).
psoriatic arthritis (1 paper, 2020). Joint inflammation associated with psoriasis. "We analyzed monocytes from healthy controls (n = 42), psoriatic arthritis (n = 25), rheumatoid arthritis (n = 16), and AS patients (n = 15) for SPPL2a enzyme activity and complemented the experiments using SPPL2a‐sufficient and ‐deficient THP‐1 cells." (PMID 32198923, 2020).
cancer (3 papers, 2022 to 2025). A tumor composed of atypical neoplastic, often pleomorphic cells that invade other tissues. "Increased exon inclusion in SPPL2A and increased exon exclusion in SMARCA1 were observed in multiple cancer types in the TCGA dataset." (PMID 41198678, 2025). "These proteins, including ICAM-1, SPPL2A, CD276, and CD44, may help the cancer cells stick together, spread, and avoid the immune system." (PMID 40805206, 2025). "To evaluate the effect of the altered expression of the CFA30 genes on cancer cell proliferation, we assessed the proliferation capability of canine MM cancer cells after silencing TRPM7, SPPL2A, GABPB1, and USP8 genes using colorimetric cell proliferation assays." (PMID 35053440, 2022).
infection (2 papers, 2025). The state of being infected such as from the introduction of a foreign agent such as serum, vaccine, antigenic substance or organism. "Similarly, pharmacological SPPL2a blockade can reshape antigen-presenting cell function, although genetic evidence shows that SPPL2a loss in humans leads to dendritic cell and B-cell defects with increased infection risk, highlighting the need for caution." (PMID 41439980, 2025).
genetic disease (1 paper, 2023). "Therefore, AGAIN identified a novel form of complete AR SPPL2a deficiency in a patient with mycobacterial disease, thereby neatly illustrating the potential of intronic AG-gain variants in the etiology of human genetic disease." (PMID 37931111, 2023).
SPPL2A also shares sentences with these, for which no sentence is quoted: Alzheimer disease (1 paper); ankylosing spondylitis (1); autoimmune disease (1); Autoimmunity (1); cutaneous melanoma (1); liver cancer (1); Mendelian susceptibility to mycobacterial diseases (1); neoplasia (1); pulmonary tuberculosis (1); rheumatoid arthritis (1).